TLR4 (toll like receptor 4)
Diseases named in the same sentence as TLR4 in open-access papers (continued):
Sharing a sentence is not in itself a finding about the gene and the disease.
tumor (continued). "Compared with the weight of xenograft tumour in GFP ctrl group (P < .01), that in TLR4 group was increased approximately by 2.5‐fold; however, compared with the weight of xenograft tumour in RNAi ctrl group (P < .01), that in TLR4i group was decreased approximately by three‐fourths." (PMID 29602239, 2018). "Various types of tumor-derived cell lines release HMGB1 in different conditions, such as glucose deprivation, leading to increased proliferation, migration and invasion of stromal cells involved in all stages of tumor progression through TLR4 activation." (PMID 29472602, 2018). "In essence, pulmonary infection with gram-negative bacteria in NSCLC patients results in TLR4 activation and IL-33 overexpression, promoting tumor progression and recurrence by enhancing cancer metabolic reprograming and cancer stem cell properties." (PMID 29568370, 2018). "Cells without TLR4 had a much weaker ability to inhibit T cell proliferation, confirming the key pro-tumor role of TLR4 in MCL cell survival." (PMID 29907126, 2018). "The results showed that TLR4 KO mice had exacerbated tumor development, similar to those seen in mice that were not treated with Salmonella Typhimurium; on the other hand, TLR5 KO mice showed a partial decrease in tumor growth." (PMID 30302344, 2018). "In conclusion, it is shown here that LPS have no impact on the clonogenicity of tumor cells, but induce a radioresistance in TLR-4 and EGFR expressing NSCLC cells." (PMID 29989005, 2018). "In addition, TLR4 activation increases expression of VEGF and TGF-β1 in prostate cancer cells, which promote tumor development." (PMID 30213077, 2018). "In in vitro studies, on U-138, A-172, LN-18 and LN-229 GBM human cell lines, we observed a significant co-localization of TLR-4 and Dkk-3, demonstrating their effective role in GBM growth which could represent a possible protective way from tumor." (PMID 30680070, 2018). "The activation via TLR2, TLR4 and TLR9 enhances IFN-γ levels, driving chemotaxis of neutrophils, DCs, and macrophages to the inoculation site, where they internalize the bacilli and/or tumor antigens, and spread through the lymphatic vessels." (PMID 29755647, 2018). "The role of TLR4 in the Prx1 induction of VEGF expression in prostate tumors has been further turned out to be dependent on the interaction of hypoxia inducible factor-1 (HIF-1) and VEGF enhancer NF-κB in tumor microenvironment." (PMID 29029545, 2017). "Considering the reported role of TNF-α and its induction via the LPS/ TLR4 axis, we asked whether this central cytokine alone may induce effects similar to LPS in the CT26 tumor model." (PMID 28445131, 2017). "Multiple groups hold the view that taxanes activate TLR4 directly as a ligand in tumor cells despite a lack of definitive evidence in tumor cells." (PMID 28915246, 2017). "In summary, APS induces the expressions of mRNAs and proteins of TLR4, TRAF-6, NF-κB and AP-1, as well as increasing the levels of TNF-α and IL-6 in the serum of the TLR4+/+ tumor-bearing mice, but not TLR4−/− tumor-bearing mice." (PMID 28303957, 2017). "Furthermore, the APS-induced TLR4, TRAF-6, NF-κB and AP-1 expression were decreased in the splenocytes of the TLR4−/− EAC tumor-bearing mice." (PMID 28303957, 2017). "The pro-lymphatic role of TLR4 is consistent with previous reports of LPS- and HMGB1-induced inflammatory lymphangiogenesis, paclitaxel-induced tumor lymphangiogenesis, and decreased ability of TLR4-deficient mice to form lymphatic vessels compared with wild-type." (PMID 28598999, 2017). "Therefore, to investigate the role of TLR2 or TLR4 in BCG-dependent AMPs release in tumor cells, we generated stable TLR2 or TLR4 knockdown lines from T24 cells and confirmed the reduced expression of TLR2 or TLR4 by Western blotting." (PMID 28881802, 2017).
tumor (continued). "For example, the crosstalk between autophagy and TLR4 signaling pathway, and the effects of propolis and its major constituents on specific inflammatory cytokines secretion in inflammation-mediated tumor are still not known." (PMID 28950845, 2017). "Moreover, this study was also designed to investigate the role and mechanism of TLR4 signaling pathway in APS-induced immunoregulation and tumor inhibition." (PMID 28303957, 2017). "Interestingly, activation of multiple TLRs using a combination of TLR3, TLR4, and TLR7 ligands resulted in tumor rejection in 50% of mice in a B16-OVA tumor model with poor immunogenicity, increasing innate immunity and CD8+ and CD4+ T-cell responses." (PMID 29190881, 2017). "Although our findings do not discount a role for TLR4 in mediating taxane-induced TNF-α production in all tumor cell types, they do suggest a distinct mechanism involving drug entry into tumor cells, with or without an indirect activation of TLR4." (PMID 28915246, 2017). "In C57BL/10J (TLR4+/+wild-type) and C57BL/6J (MyD88+/+wild-type) tumor-bearing mice, the tumor apoptosis rate, immune organ indexes and the levels of TNF-α, IL-1β and IL-6 in blood increased and the tumor weight decreased by oral administration of APS for 25 days." (PMID 28303957, 2017). "Zitvogel proved that dead tumor cells could release HMGB1, thus activating tumor-specific T cell immunity, and inducing antitumor effect via toll-like receptor 4 stimulating dendritic cells." (PMID 28968989, 2017). "In summary, we demonstrate a strategy to restore the local immunosurveillance in the tumour microenvironment by application of two readily-acquired cationic polymers, C-dextran and PEI, which re-polarize MDSCs from M2- to M1-type through TLR4-mediated signalling." (PMID 27074905, 2016). "TLR4 is not only important in the regulation of immune responses to infection, but also is involved in noninfectious inflammatory diseases, such as tumor invasion and survival." (PMID 26675260, 2016). "Although LPS-induced TLR4 activation does not take place as a result of a tumor, it is possible that other tumor-derived factors can activate platelets via TLR4." (PMID 27708646, 2016). "Compared with TLR4−/− mice, knockdown of TLR4 in Hepa1-6 cells resulted in more inhibition of lung metastasis in mice, suggesting that TLR4 expression in HCC cells is more important than other cells in the host to mediate tumor metastasis." (PMID 27623211, 2016). "Expression or upregulation of TLR4 has been identified in tumor cells, and although it is not always the case, TLR4 activation is mostly reported to stimulate cancer cell aggressive behavior." (PMID 27909407, 2016). "However, TLR4 signaling also induces cytokines (IFN) that have antitumor effects by induction of TRAIL, a potent inducer of tumor cell death." (PMID 27389279, 2016). "During inflammation, cell migration and tumor metastases, HMGB1 serves as an extracellular cytokine and mediates a series of signaling molecules by binding to its membrane receptors, including RAGE, TLR4 and TLR2." (PMID 27899819, 2016). "Replacement of the radiosensitive haematopoietic compartment with TLR-2/-4−/− or TLR-9−/− cells did not affect tumour formation, in contrast to the role of TLR-4 on haematopoietic and non-haematopoietic cells in chemically induced skin carcinogenesis." (PMID 25575023, 2015). "TLR-4 is required for the IL-12 response in these mice and mice lacking TLR-4 are suspectible to MuPyV tumor induction, likely due to a loss of IL-12 secretion." (PMID 26474471, 2015). "Indeed, the FDA recently approved the TLR2/TLR4 agonist Bacillus Calmette-Guérin (BCG), the TLR2/TLR4 agonist monophosphoryl lipid A (MPL) and the TLR9 agonist imiquimod as anti-tumor agents." (PMID 25871398, 2015). "Both S100a8 homodimers and calprotectin signal via Toll-like receptor-4 (Tlr4), consistent with expression of Tlr4 in all four tumour lines (data not shown)." (PMID 25633981, 2015).
tumor (continued). "In tumour environment, VEGF-A Ab led to the similar inhibition of angiogenesis, and the increasing secretion of VEGF-A was inhibited by antibodies of ds-HMGB1, TLR4 and RAGE." (PMID 26099505, 2015). "Recently, a number of studies have indicated that activation of TLR4 by LPS might elevate CXCR4 and/or CXCR7 expression in tumor cells, enhancing the response to SDF-1 to promote invasion and cell dissemination." (PMID 26288180, 2015). "In vivo PSP as well as Adriamycin (ADM) decreased the mean weights of tumors compared with normal saline and PSP increased thymus index and spleen index relative to ADM in tumor-bearing C57BL/10J (TLR4+/+) mice but not in C57BL/10ScCr (TLR4-/-) mice." (PMID 26032186, 2015). "Thus, tumor cell-derived HA fragments through TLR4/PI3K signaling induce early activation and longevity of tumor neutrophils, which in turn stimulate the motility of malignant cells." (PMID 25926834, 2015). "In contrast, the therapeutic effect of BLS is independent of mice TLR4 and it is only achieved when mice are injected shortly after tumor cells are injected." (PMID 25973756, 2015). "Particularly, PAUF binds to TLR2 and TLR4 inducing an increase in expression of AP-1 regulated genes in THP-1 cells yet does not activate the NFkB pathway, resulting in promotion of escape from innate immune surveillance and tumor growth." (PMID 26336989, 2015). "In comparison, both Dox-TCL- and SK-TCL-pulsed DCs expressed much higher levels of expression of CD91, TLR2 and TLR4 than those detected in immature or Naive-TCL loaded DCs, suggesting specific ICD component proteins from treated tumor cells can stimulate the expression of these PRRs." (PMID 26403780, 2015). "The induction of autophagy via the injection of rapamycin with or without the TLR4/9 agonist complex into the tumor attenuated metastasis." (PMID 25743109, 2015). "This study showed the relevance of interactions between TLR4, NLRP3 and NOD1 in LM-induced DC maturation and anti-tumor responses, which help us understand the immune regulatory mechanisms involved in LM vaccine-related tumor immunotherapy." (PMID 25826093, 2015). "The median time to recurrence for patients with tumours that expressed TLR4 was 12 months (n = 20), whereas TLR4 negative tumours recurred in a median time of 27 months (n = 19); p = 0.016." (PMID 24977712, 2014). "The difference in OS between TLR4 positive (n = 19) and TLR4 negative tumours (n = 14) was not statistically significant (p = 0.312)." (PMID 24977712, 2014). "There was more metastasis in TLR3 expressing tumor cells, TLR4 expressing inflammatory cells but not in TLR9 expressing fibroblasts like cells." (PMID 24904578, 2014). "Expression of TLR4 and MyD88 were assessed in situ on paraffin sections of normal ovarian tissue adjacent to tumor (n=12) and borderline (n=8) and malignant (n=24) tumors." (PMID 24527095, 2014). "The activation of the TLR4 signaling pathway induces TNF-α and NF-κB, leading to the promotion of CRC; TNF-α knockout mice treated with AOM/DSS show significantly less tumor formation, representing the pro-tumorigenic role of TNF-α." (PMID 25076949, 2014). "The importance of these interactions in tumour development was illustrated in experiments in knock-out mice showing that in the absence of S100A9 or TLR4, the development of spontaneous prostate cancer tumours was delayed." (PMID 24162378, 2014). "For the first time, the effects of GNPs were explored on the model of LPS-induced maturation of human DCs and the maturation induced by necrotic tumor cells generated at conditions similar to those induced in GNP-based photo-thermal therapy, both of which activate a TLR4 signaling pathway." (PMID 24802102, 2014). "In addition, TLR4 activation increases expression of VEGF and TGF-β1 in PC3 cells, which promote tumor development." (PMID 25101092, 2014). "This indicated that TLR2 and TLR4 were present mainly in the tumor-infiltrating inflammatory cells, not in cancerous tissues." (PMID 25547486, 2014).
tumor (continued). "Knockdown of TLR4 inhibited LMW-HA-induced expression of CXCR7 in tumor masses, indicating that CXCR7 was induced by LMW-HA in tumor tissue through TLR4 and might play important roles in tumorigenicity." (PMID 24363762, 2013). "Tumor size tended to be larger in cases with high rather than low expression of TLR4 (P < 0.001) and CXCR7 (P < 0.001)." (PMID 24363762, 2013). "In addition to CD14-and TLR4-dependent LPS-signaling, activation of the EGFR seems to be a crucial element of the observed tumor cell proliferation." (PMID 22923191, 2013). "However, DC/tumor-derived TGF-β1 reduces the efficacy of CTL induction, even when stimulated with combined TLR2 and TLR4 agonists in vitro." (PMID 23555011, 2013). "In our studies, we hypothesized that the effects of the early tumor microenvironment, represented by BALF from BHT-treated mice, would produce TLR4-dependent changes in cultured pulmonary epithelium that will include differential inhibition of GJIC." (PMID 25035812, 2013). "In this context, it is of interest that soluble BGN serves as a ligand for TLR4 and TLR2, which might explain some of the anti-tumor effects of BGN." (PMID 24223213, 2013). "Interestingly, both RAGE and TLR4 have been shown to play a role in the control of tumor growth in different systems, and it has also been shown that inhibition of S100A9/TLR4 interactions can inhibit tumor growth." (PMID 23667563, 2013). "Thus, the reduced tumor growth observed in S100A9−/− and TLR4−/− animals correlate with low TGFβ RNA expression in splenic CD11b+ cells." (PMID 22470535, 2012). "The TLR4 and MyD88 expression were evaluated in human EOC cell lines and tumor sections." (PMID 22533866, 2012). "Tumors with high TLR3 expression by tumor cell or with high TLR4 expression by mononuclear inflammatory cells (MICs), but not TLR9 high fibroblast like cells were significantly associated with higher probability of metastasis." (PMID 22295250, 2012). "Thus, S100A9 and TLR4 appear to be involved in promoting tumor growth in two different tumor models and pharmacological inhibition of S100A9-TLR4 interactions is a novel and promising target for anti-tumor therapies." (PMID 22470535, 2012). "The rational for this approach was that critical mediators should show the same deviation in TLR4−/− and S100A9−/− animals compared to C57BL/6 controls if they could be involved in the observed in vivo effect on tumor growth regulation." (PMID 22470535, 2012). "It is undisputed that the presence or absence of TLR4 expression on tumor (as well as nontumor) cells can influence different stages of carcinogenesis." (PMID 22110526, 2011). "Correlation of combined high expression of TLR4, MD-2, and CXCR7 with tumor size and metastasis." (PMID 22180778, 2011). "The incidence of tumor size tended to be higher in cases with high rather than low expression of TLR4, MD-2, and CXCR7 (p = 0.003, p<0.001, p = 0.013, resp.)." (PMID 22180778, 2011). "Its mechanism of action apparently involves TLR4 activation, since OKA-432 does not inhibit tumor growth on TLR4 knockouts as it does on wild-type mice." (PMID 22110526, 2011). "While implant shells themselves do not directly stimulate tumor growth, they may act as passive carriers for bacteria, with biofilm-derived lipopolysaccharide (LPS) interacting with TLR4 to promote inflammatory cytokine release and tumor progression." (PMID 41517575, 2026). "Sgg can enlist CD11b+TLR4+ cells, promoting the expression of IL-8, COX-2, and IL-1, and escalating the levels of tumor progression-related transcription factors like β-catenin, c-Myc, and PCNA, thereby driving inflammation and facilitating tumor proliferation." (PMID 40370465, 2025). "CD36 also demonstrated positive correlations with immune checkpoint molecules, including C10orf54, EDNRB, TLR4, ENTPD1, IL10, and IL2RA, suggesting that it may contribute to immune escape mechanisms by engaging checkpoint pathways in the tumor microenvironment." (PMID 41550652, 2025).
tumor (continued). "The discrepancy between the expression levels of TLR4 and TLR8 and the data obtained from in silico analysis could be due to the different origins, since the gene expression was evaluated in PBMC while bioinformatic dataset was obtained from tumor tissues." (PMID 40025339, 2025). "However, in other tumors linking LPS in the activation of TLR4 on tumor cells was not possible suggesting there are other endogenous ligands that activate TLR4 on tumor cells." (PMID 40124677, 2025). "It has been reported that tumour‐released HSP90 and HSP70 trigger muscle atrophy through activation of TLR4, and HSP90 inhibitors can effectively alleviate skeletal muscle consumption caused by CC, indicating HSP90 may be the potential therapeutic target for attenuating CC." (PMID 40170230, 2025). "Similarly, TLR4 signaling via its adaptor molecule TRIF contributes to the production of type I interferons and inflammatory cytokines, fostering an immunosuppressive tumor microenvironment." (PMID 40922674, 2025). "Furthermore, TLR-4 and other innate sensors in immune cells that are not activated properly can lead to unresolved inflammation, which can lead to tumor progression and metastasis." (PMID 40002869, 2025). "Notably, IBC samples showed higher intensity of TLR4 expression not only in the tumors but also in surrounding non-tumor tissues (92.4 ± 18.5) compared with surrounding non-tumor tissues from the non-IBC group (61.2 ± 18.7; p < 0.05)." (PMID 40647480, 2025). "Through the combination of network pharmacology and in vivo and in vitro experiments, this study found that Gomisin B in YGS may target Toll-like receptor 4 (TLR4), and sensitize CRC stem cells via the NF-κB signaling pathway, inhibit tumor immune escape, and suppress the EMT process." (PMID 40247422, 2025). "Interestingly, they proposed that necrotic or stressed tumor cells release HMGB1 into the urinary space, where it may engage pattern-recognition receptors (e.g., RAGE, TLR4) to sustain a pro-inflammatory, tumor-promoting environment." (PMID 41009692, 2025). "Moreover, tumor-derived exosomes (TEXs) can actively polarize neutrophils toward the N2 phenotype and promote autophagy via the high mobility group protein 1 (HMG-1)/toll-like receptor 4 (TLR4)/NF-κB signaling pathway, facilitating immune escape and tumor survival." (PMID 40427384, 2025). "Additionally, the antitumor effects of NaB were associated with the suppression of tumor cell proliferation and migration, an increase in the rate of tumor cell apoptosis, the modulation of the gut microbiota, and the inhibition of the HDAC/TLR4/MyD88 signaling pathway." (PMID 41251471, 2025). "However, through its interaction with TLR4 on these cells, local CXCL10 can drive their reprogramming toward a pro-inflammatory, anti-tumoral M1 phenotype, thereby shifting the TME from a state that supports tumor growth to one that actively suppresses it." (PMID 41516196, 2025). "The interaction between HMGB1 and TLR4 can mediate signal transduction of the inflammatory response via MYD88, which activates the NF-κB signaling pathway, leading to the release of inflammatory factors, and ultimately triggering tumor antigen-specific T-cell immunity." (PMID 37897664, 2024). "Moreover, the TLR4 signaling pathway activation has been noted to foster the growth, mobility, and invasive capabilities of HCC cells, hinder programmed cell death, and accelerate resistance to tumor drugs." (PMID 38933262, 2024). "Recent studies have shown that macrophages M2 polarization relies on TLR4-MyD88-p38-STAT3 signal transduction, which effectively inhibits the proliferation of cluster of differentiation CD4+ and CD8+ T cells in vitro and promotes tumor growth in vivo, mainly through PD-L1." (PMID 38785969, 2024).